IL16 (interleukin 16)
Diseases named in the same sentence as IL16 in open-access papers (continued):
Sharing a sentence is not in itself a finding about the gene and the disease.
tuberculosis (1 paper, 2024). A chronic, recurrent infection caused by the bacterium Mycobacterium tuberculosis. "The expression levels of certain genes related to anti-tuberculosis were further confirmed, such as CCL1, IL15, IL16, ISG15, GBP5, IL23, ATG2A, IFNβ, and CSF3." (PMID 38392218, 2024). "Subsequently, we further verified the transcription levels of genes on anti-tuberculosis-related genes such as CCL1, IL15, IL16, ISG15, GBP5, IL23, ATG2A, IFNβ, and CSF3." (PMID 38392218, 2024). "Rv1476 overexpression inhibited the expression of some anti-tuberculosis-related genes, such as CCL1, IL15, IL16, ISG15, GBP5, IL23, ATG2A, IFNβ, and CSF3." (PMID 38392218, 2024).
urolithiasis (1 paper, 2023). Stone(s) within the urinary tract. "However, there was no causal association between other common risk factors (PTH, CRP, IL6, IL18, IL27, IL8, IL16, IL1Ra, coffee consumption, age of smoking initiation, smoking initiation, and cigarettes smoked per day) and urolithiasis in the meta-analysis." (PMID 37624788, 2023).
urticaria (1 paper, 2023). A vascular reaction of the skin characterized by erythema and wheal formation due to localized increase of vascular permeability. "On the other hand, when immune skin diseases served as the exposure variable, LP affected eotaxin, IL-12p70, IL-4, IL-16, and MCP-1 and urticaria affected IL-2 and MCP-1." (PMID 37954607, 2023).
viral hepatitis (1 paper, 2014). An acute or chronic inflammation of the liver parenchyma caused by viruses. "Due to this, phenomenon variations occurring in Il-16 gene sequence could affect its function and cause deregulation in immune response against viral hepatitis." (PMID 25692036, 2014).
viral meningitis (1 paper, 2019). Inflammation of the membranes surrounding the brain and spinal cord due to a viral infection. "Both, bacterial and viral meningitis additionally displayed significantly elevated concentrations of the cytokines CCL1, CCL19, CCL20, CXCL2, CXCL6, IFNγ, and IL16." (PMID 31727097, 2019).
vitamin A deficiency (1 paper, 2015). Deficiency of vitamin A due to malnutrition, malabsorption, or dietary lack. "Thus, we can speculate that vitamin A deficiency may favor the expression of IL-16 and IL-23 receptors in adoptively transferred iTreg cells during intestinal inflammation in the gut." (PMID 26583087, 2015).
tumor (104 papers, 2011 to 2026). "Complementary research using a laying hen model of spontaneous OC demonstrated that IL-16, known for its proangiogenic properties, is associated with OC development and tumor-associated neoangiogenesis." (PMID 39408600, 2024). "IL-16 expression was increased in TTP-deficient 3D tumor spheroids, and elevated IL-16 levels enhanced the infiltration of monocytes into tumor spheroids." (PMID 30380668, 2018). "Emerging evidence suggests that expression of interleukin 16 (IL-16) by the tumor epithelium and microvessels increases in association with OVCA development and offers a potential target for early OVCA detection." (PMID 26161406, 2015). "To further address the mechanisms underlying this effect, we investigated whether tumor-intrinsic Aurora-A can modulate CD8+ T cell cytotoxicity by regulating IL-16 production." (PMID 38291041, 2024). "Furthermore, IL-16 is abundantly expressed in various tumor cells and favorably linked with Gleason score and clinical stage in prostatectomy tumor tissues of PCa patients." (PMID 38745115, 2024). "In addition, elevated serum IL16 levels are significantly associated with tumor recurrence and poor prognosis of GC." (PMID 34968167, 2022). "Moreover, increase in IL-16 expression was associated with its regulator microRNA miR-125a-5p, also a tumor suppressor microRNA." (PMID 35497879, 2022). "In addition, IL-16 can activate the secretion of tumor-associated inflammatory cytokines, such as TNF-α, IL-1β, IL-6, and IL-15, all of which are major factors involved in tumorigenesis." (PMID 25954818, 2015). "IL-16 is a proangiogenic factor suggested to stimulate tumor-associated angiogenesis." (PMID 26161406, 2015). "In cancers, loss of nuclear IL-16 leads to hyperproliferative states, which are more difficult to target, but neutralization of secreted IL-16 could improve outcomes of chemotherapy and modulate tumor escape mechanism." (PMID 40529362, 2025). "Additionally, IL-16 signaling may influence cancer-associated fibroblasts and extracellular matrix remodeling, further facilitating tumor invasion and metastasis." (PMID 39201599, 2024). "Overall, our results demonstrate that tumor-regenerating MM cells may be particularly susceptible to IL-16 neutralization, suggesting an important role of anti-IL-16 therapies in the treatment of MM, in particular in a sequential combination with existing strategies targeting the bulk of MM cells." (PMID 28512269, 2017). "Moreover, IL-16 has also been reported as a proangiogenic factor and may also be expressed by the endothelium of tumor-associated microvessels." (PMID 26161406, 2015). "Spatial mapping revealed spatial association of RCC progression-associated cancer and immune cell subpopulations, suggesting the potential role of the VEGF, GDF, PTN and IL16 pathways in the remodeling of the tumor microenvironment." (PMID 42196432, 2026). "For example tumor intrinsic Aurora-A promotes the cytotoxic activity of CD8+T cells in immune-hot chemotherapy resistant cancer (CRC) via negative regulation of interleukin-16 (IL-16)." (PMID 40529362, 2025). "We observed that IL-16, IL-17, IL-22, and IL-26 are specifically expressed in Tc17 cells, and their corresponding receptors are also highly expressed in tumor cells." (PMID 40452847, 2025). "The ligand IL16 was highly expressed specifically in IBC tumour B and T cells, whereas its receptor (CD4) was expressed mainly in myeloid cells." (PMID 40624675, 2025). "Pro-inflammatory cytokines such as IL-6, IL-8, IL-16, and IL-32 were included due to their involvement in tumor growth, angiogenesis, and chemoresistance." (PMID 40652770, 2025). "Our data indicate that Tc17 cells highly express a range of cytokines, notably IL-16, IL-17A, IL-17F, IL-22, and IL-26, and it is these five cytokines for which receptors are also highly expressed in tumor cells." (PMID 40452847, 2025).
tumor (continued). "The upregulation of IL-16 was suggested as tumor escape mechanism and impaired the therapeutic effect of Aurora-A inhibition." (PMID 40529362, 2025). "Interleukin-16, a multifunctional cytokine, plays a key role in inflammatory diseases and contributes to tumor development and progression." (PMID 39886381, 2025). "Our results showed that the negative regulation of IL-16 by tumor-intrinsic Aurora-A is a universal mechanism in CRC cells." (PMID 38291041, 2024). "This study found that neutralizing IL-16 in Aurora-A knockdown CT26-derived tumors can inhibit tumor growth by promoting the cytotoxicity of CD8+ T cells." (PMID 38291041, 2024). "The results showed that anti-IL-16 antibodies attenuated tumor growth and enhanced antitumor immune populations." (PMID 38291041, 2024). "This study reveals that tumor intrinsic Aurora-A can modulate anti-tumor immunity by negatively regulating IL-16 expression in the tumor microenvironment (TME)." (PMID 38291041, 2024). "The results demonstrated that the combination of anti-IL-16 antibodies with MLN8237 results in decreased tumor growth, augmented infiltration of CD8+ T cells, and reduced infiltration of CD4+ T cells." (PMID 38291041, 2024). "Systemic inhibition of Aurora-A by MLN8237 can suppress tumor growth in immunocompetent mice, with a concomitant increase of IL-16 in tumors." (PMID 38291041, 2024). "IL-16 stimulates the production of pro-inflammatory cytokines, which would also support anti-tumor immunity." (PMID 38812776, 2024). "Our studies demonstrate that tumor-intrinsic Aurora-A promotes antitumor immunity by inhibiting IL-16 production in high immune cell-infiltrated tumors." (PMID 38291041, 2024). "Aurora-A in tumor cells can influence tumor growth by regulating antitumor immunity through inhibiting IL-16 expression in the immune hot TME." (PMID 38291041, 2024). "We postulate that combining Aurora-A kinase inhibitors with IL-16 antibodies will be a useful therapeutic strategy for cancer patients with high tumor-intrinsic Aurora-A expression and high lymphocyte infiltration." (PMID 38291041, 2024). "Combinational treatment of IL-16 neutralizing antibodies improves the anti-tumor effect of Aurora-A inhibitor." (PMID 38291041, 2024). "Several mediators play essential roles in the MM angiogenic process, leading to tumour growth, invasion, and metastasis, according to extensive study; for example, increased levels of Interleukin-16 (IL-16) and IL-17 result in a poor MM prognosis." (PMID 37937298, 2023). "Il1b expression also increased in DCs and MonoMacs, whereas βA-expressing tumor cells showed also elevated levels of Il16 mRNA." (PMID 38304252, 2023). "and IL16 expression was negatively correlated with miR-128-3p expression and positively associated with CD4 + T cells infiltration in 402 tumor samples from TCGA cohort." (PMID 34968167, 2022). "Among the 14 molecules defining the signature, IL-16 was one of the most important in discriminating tumor versus juxta-tumor tissues, as shown by its high tumor signature coefficient." (PMID 36539890, 2022). "For almost all patients, IL-16 was detected at higher quantities in the tumor supernatant compared to the juxta-tumor, while the tumor-specific high FGF-2 levels were highly patient-dependent." (PMID 36539890, 2022). "Interleukin-17A (IL-17A) is produced by Th17 cells which infiltrate the tumor microenvironment and induces the expression of several inflammatory cytokines including IL-1β, IL-16 and IL-23, leading to variable effects on tumor growth at different stages." (PMID 36135194, 2022). "IL16 is highly overexpressed in multiple solid tumors, and its overexpression is closely related to tumor occurrence, development, metastasis, and poor prognosis." (PMID 34968167, 2022). "In contrast, co-culture with MF tumor-derived fibroblasts significantly increased IL16 expression in MyLa cells (p < 0.01)." (PMID 33941102, 2021).
tumor (continued). "Other cytokines that consistently showed significant inhibition by muscle‐specific SIRT6 over‐expression in tumour settings were IL‐1α and IL‐16." (PMID 34212132, 2021). "It has been reported that M1 macrophages can secrete INF-γ, IL-16, IL-12, and other proinflammatory cytokines, starting the inflammatory response and killing tumor cells." (PMID 34512654, 2021). "Cytokine analysis in tumor patients revealed comparatively lower levels in IL-16, IL-18, CXCL8 (IL-8), IL-9, and CXCL10 (IP-10), indicating that the higher T cell numbers were not accompanied by increased T cell activity." (PMID 30740106, 2019). "CD48, SEPT1, ACAP1, PPP1R16B, and IL16 were all negatively correlated with tumor purity, supporting the results for highly correlating with ICILs." (PMID 31737562, 2019). "Apparently, further studies are needed to determine the direct effect of TTP on IL-16 expression, but it seems clear that the loss of TTP allows immune cells within the microenvironment to promote tumor growth." (PMID 30380668, 2018). "We have previously identified IL-16 as an important factor promoting the malignant phenotype of tumor cells from MM patients." (PMID 28512269, 2017). "Establishing an inducible knockdown system and performing gene expression arrays we observed an association between IL-16 expression and activation of PI3, NFκB and MAP kinase pathways and, specifically, genes involved in tumor cell proliferation." (PMID 28512269, 2017). "Out of all our analyses on the effects of stable IL-16 knockdown on MM cells, the most important observations were the consequences IL-16 withdrawal had on the clonogenic subpopulation within the bulk of tumor cells." (PMID 28512269, 2017). "IL-16 is a pro-inflammatory and pro-angiogenic cytokine which is produced by lymphocytes and some epithelial cells, probably also by tumor cells, and attracts CD4+ cells, especially T-cells." (PMID 27665539, 2016). "Fourth, in breast cancer depletion of TTP augments levels of IL-16, which promotes monocyte and macrophage tumor infiltrates and tumor progression." (PMID 27825143, 2016). "All hens were euthanized following IL-16-targeted contrast imaging and sonographic predictions and stages of the tumor were confirmed by gross examination of hens at necropsy." (PMID 26161406, 2015). "In contrast, in addition to the expression of IL-16 by the tumor epithelium and the microvessels, IL-16 is also secreted into the circulation." (PMID 26161406, 2015). "IL-16 expressing cells were detected in the stroma of normal or tumor-bearing ovaries and in the tumor vicinity including spaces between tumor glands." (PMID 26161406, 2015). "Elevated IL-16 prior to resection could reflect a tumor-driven inflammatory response, although the functional implications of this remain to be fully clarified." (PMID 40860824, 2025). "In contrast, IFN-γ, IL-16, IL-1ra, IL-8, and IL-9 were related to tumor cell type." (PMID 41048959, 2025). "Higher IL16 expression in tumor tissue may indicate greater immune system activation, which could enhance the patient’s prognosis." (PMID 39886381, 2025). "In bladder cancer it was shown that IL-16 enhances the suppressive T regs capacity within sentinel lymph nodes and could contribute as tumor immune escape mechanism." (PMID 40529362, 2025). "This study demonstrated that tumor-intrinsic Aurora-A in cancer cells could promote antitumor immunity by inhibiting IL-16 secretion in immune hot tumors." (PMID 38291041, 2024). "In conclusion, combining an Aurora-A inhibitor with IL-16 neutralization may represent a promising strategy for CRC patients with high tumor-intrinsic Aurora-A and tumor-infiltrating lymphocytes." (PMID 38291041, 2024). "Therefore, neutralizing IL-16 with specific antibodies decreases tumor growth and enhances CD8+ T cell cytotoxicity in Aurora-A knockdown CT26-derived tumors." (PMID 38291041, 2024).
tumor (continued). "Thus, even discrete changes in IL-16 structure and function can modulate immune response, influence the tumor microenvironment, and impact cancer cell behavior." (PMID 39408600, 2024). "We demonstrated that tumor-intrinsic Aurora-A might promote antitumor immunity by inhibiting IL-16 secretion in immune hot TMEs." (PMID 38291041, 2024). "Indeed, MLN8237 inhibited tumor growth in 8-week-old Balb/c mice and led to an increased IL-16 expression in CT26-derived tumors." (PMID 38291041, 2024). "However, only in CRC with high lymphocyte infiltration (hot tumor), tumor-intrinsic Aurora-A can promote antitumor immunity via inhibiting the IL-16-mediated immune suppression pathway." (PMID 38291041, 2024). "We hypothesized that systemic Aurora-A inhibition may impair MDSC function, thereby promoting anti-tumor immunity; the increased expression of IL-16 in systemic Aurora-A inhibitor-treated mice might counteract this beneficial effect." (PMID 38291041, 2024). "Inhibition of tumor-intrinsic Aurora-A reduces anti-tumor immunity by upregulating IL-16 in CRC." (PMID 38291041, 2024). "In summary, these studies demonstrated that miR-128-3p could serve as an essential regulator of tumor immunity by modulating the enrichment of CD4+ CD25+ Foxp3+ Tregs by targeting IL16 expression in GC." (PMID 34968167, 2022). "Six pathways were specifically active in tumors compared to PBMC, including known inflammatory signals MIF, TNF, and IL16, suggesting that these pathways might critically contribute to tumor progression." (PMID 35812372, 2022). "We hypothesized that miR-128-3p may influence CD4+ Treg differentiation by regulating tumor cell release of the cytokine interleukin 16 (IL16)." (PMID 34968167, 2022). "Overall, with this bidimensional analysis we could show that tumor samples were well characterized by high secretions of IL-16, HGF, the TGF-β1, 2 and 3, SCF, FGF-2 and VEGF, and low secretions of CCL8 and Leptin." (PMID 36539890, 2022). "Moreover, activated STAT3 motivates the secretion of many chemokines and cytokines such as, IL-6 and IL-16 to maintain activation of immune cells in the tumor tissue." (PMID 36374927, 2022). "Moreover, neutrophils can also secrete IL-16 and transferrin to accelerate metastasis and remain stemness of tumor cells." (PMID 33178575, 2020). "Neutrophils may promote 4T1 cell adhesiveness, invasiveness, and migration by secreting cytokine IL-16, while instillation of an IL-16 neutralizing antibody reversed the effects of neutrophil on tumor cells." (PMID 30962764, 2019). "Moreover, many IL-16-expressing cells were localized in the stromal tissue surrounding the cysts and tumor in PCOC hens." (PMID 30596106, 2018). "Our findings suggest that IL-16 also can be produced by tumour cells." (PMID 28417956, 2017). "Next, we asked the question whether we would also find secretion of IL-16 by the majority of tumor cells at any given timepoint and we used an ELISPOT assay to determine cytokine release on a single cell level." (PMID 28512269, 2017). "In addition to stromal cells of the tumor, tumor epithelium has also been reported to express IL-16." (PMID 26161406, 2015). "However, C5/C5a and IL-16 remained unchanged by MEK inhibition in tumor lysates." (PMID 38458648, 2024). "However, the roles of IL-16 in tumor progression are poorly understood, and the role of IL-16 in antitumor immunity within the TME remains unclear." (PMID 38291041, 2024). "Further analysis showed increased production of proinflammatory interleukins such as IL‐1β and IL‐16 and accumulation of various chemotactic agents, including CCL3, CCL4, CCL5, CXCL9, CXCL10, and CXCL11, in the tumor tissue." (PMID 41221154, 2025). "Once in close proximity to the tumor cells, these Tc17 cells engage in a reciprocal signaling cascade, secreting interleukins (IL-16, IL17, IL-22, and IL-26), thereby forming a vicious cycle that promotes the progression of tumor cells." (PMID 40452847, 2025).